FGF1 (fibroblast growth factor 1)
Diseases named in the same sentence as FGF1 in open-access papers (continued):
Sharing a sentence is not in itself a finding about the gene and the disease.
tumor (186 papers, 2002 to 2026). "The dysregulation of FGF-1 signalling is not only implicated in tumorigenesis but is also associated with tumour invasion and metastasis." (PMID 40709999, 2025). "Our findings indicated favorable associations for FGF1 expression with reduced tumor size, lower grade, hormone receptor positivity, and increased OS." (PMID 39302921, 2024). "We chose to further investigate FGF1 because of our previous work that showed elevated production during adipose tissue expansion and association with tumor FGFR activation and weight gain in HFD-fed females." (PMID 37608351, 2023). "Since FGF1 is associated with inflammation in the tumor microenvironment, we next analyzed the potential correlation between AKR1B10 and FGF1 in TCGA datasets." (PMID 32615540, 2020). "Deregulation of FGF-1 signaling is not only implicated in tumorigenesis but also is associated with tumor invasion and metastasis." (PMID 24829797, 2014). "CXCL12high iCAF was also associated in tumor growth by FGF1/7/10 and CXCL12 interactions." (PMID 38892065, 2024). "Another study shows that the adoptive transfer of MDSCs to HCC-bearing mice not only promotes HCC progression, partially by activating tumor-associated fibroblasts via IL-6/fibroblast growth factor 1 (FGF1) signaling, but also induces resistance to sorafenib treatment." (PMID 38397901, 2024). "FGF-1, -11, -18 expression in tumor tissues was associated with MBD." (PMID 37546410, 2023). "Meanwhile, elevated FGF1 expression level in tumor tissues was associated with poor prognosis." (PMID 34552869, 2021). "Considering the fact that the proteins encoded by the EFNB2 and FGF-1 genes act in multiple ways on stimulating tumor angiogenesis, β-escin may negatively influence angiogenesis by down-regulating these genes." (PMID 29342121, 2018). "Furthermore, FGF1 has been associated with tumor growth in nude mice injected with ovarian cells overexpressing FGF19." (PMID 29467390, 2018). "In addition, since FGF-1 has been similarly associated with highly vascularised tumours, FGF-1-overexpressing transfectants were included for comparison." (PMID 14735189, 2004). "Firstly, Kaplan–Meier survival analysis based on TCGA data revealed that FGF1 gene expression statistical significantly correlates with ccRCC patients overall survival, higher FGF1 expression was associated with better survival, suggesting its potential tumor suppressor function." (PMID 33865387, 2021). "Although implicated in many biological processes, such as export of FGF1 and IL1‐α and tumour angiogenesis, the exact function of S100A13 in skeletal muscle remains elusive." (PMID 41582615, 2026). "Inhibition of RORγ markedly decreased FGF1 levels in conditioned media, whereas exogenous FGF1 restored tumor growth." (PMID 41430037, 2025). "Mechanistically, MDSCs drive sorafenib resistance by upregulating fibroblast growth factor 1 (FGF1), which activates CAFs to sustain tumor growth." (PMID 41438763, 2025). "In our study, both FGF1 siRNA and RORγ antagonists reduced FGF1 expression and suppressed tumor cell survival." (PMID 41430037, 2025). "The positive diffuse stromal immunostaining for FGF1 suggested a possible functional role for FGF1 secreted by tumor cells in the proliferation of stromal fibroblasts or other mesenchymal cell types." (PMID 40806365, 2025). "AKR1B10 exerts a tumor-suppressive effect in CRC by inactivating FGF1 and represents a novel target for combination therapy in CRC68." (PMID 41006647, 2025). "SDC1 exhibited a greater tumor mutational burden (TMB) score, while ERBB2, KDR, FGF2, KIT, FGFR1, and FGF1 showed lower TMB scores." (PMID 38189813, 2024). "Overexpression of fibroblast growth factor (FGF) family proteins, such as FGF1 and FGF11, is associated with tumor growth, progression, invasion, and metastasis." (PMID 38339062, 2024).
tumor (continued). "The smooth muscle cells, fibroblasts, and B cells exhibited high expression of FGF1, while tumor cells, smooth muscle cells, T cells, and B cells highly expressed FGFR1." (PMID 38407266, 2024). "αVβ3 (integrin αV:β3) is crucial in IGF‐1 (insulin‐like growth factor‐1) and FGF‐1 (fibroblast growth factor‐1) signaling, both of which are polypeptides involved in tumor progression of certain cancers." (PMID 38958135, 2024). "FGF1 mutants defective in integrin binding strongly blocked angiogenesis in vitro and tumor growth in vivo." (PMID 38391921, 2024). "In contrast to our findings, FGF1 expression has been shown to induce tumor growth and metastasis in previous studies." (PMID 39302921, 2024). "Our mice model data showed that Fgf1 was significantly increased in the CRC complicated with DM group compared with the only CRC tumor group." (PMID 36999930, 2023). "High FGFR1 expression in tumor tissues is associated with less favorable tumor characteristics, and FGF ligand (FGF1, FGF11, FGF18) expression is associated with MBD." (PMID 37546410, 2023). "Other known ligands are also galectin-3, fibrinogen-like protein 1 (FGF-1) and L-selectin presence on tumour cells." (PMID 36980527, 2023). "The fibroblast growth factor-1 and IL-1 are known to be involved in angiogenesis, inflammation, and tumor metastasis." (PMID 36793711, 2023). "A potential role for granzyme B released from mast cells in the regulation of the extracellular matrix in vivo is the degradation of the extracellular matrix of tumours, thereby releasing FGF-1 and GM-CSF and promoting angiogenesis." (PMID 36342273, 2022). "CAFs can further secrete FGF1 to actively participate in tumor-stromal crosstalk and further drive tumor progression." (PMID 36064310, 2022). "First of all, we demonstrated that treatment with the combination of RES and FGF1 enhanced the inhibitory effect of DOX on tumor cell proliferation." (PMID 36110535, 2022). "Here, we extend these findings to show that preventing weight gain is sufficient to reduce FGF-1 in the tumor microenvironment and decrease activation of FGFR in tumors." (PMID 35725493, 2022). "In the tumour tissue of the same mice, decreased levels of FGF1, TGF‐β and Ang‐4 were also observed." (PMID 35701366, 2022). "In brain tumors, such as gliomas, FGF1 is involved in chemotaxis and migration of tumor cells which primarily express the FGF1B and FGF1D isoforms." (PMID 35784465, 2022). "Accumulating evidence indicates that FGF1 promotes tumour development by facilitating cell proliferation, migration, invasion and angiogenesis." (PMID 35864158, 2022). "Here, we demonstrated a novel molecular pathway whereby activation of COX4I2 significantly induces fibroblast growth factor 1 (FGF1) expression and thus promotes tumor-associated angiogenesis and the activation of cancer-associated fibroblasts (CAFs)." (PMID 36064310, 2022). "Age, gender, neural invasion, vascular invasion, tumor size, differentiation, T stage, N stage, M stage and FGF1 expression were used to estimate 3- and 5- year OS." (PMID 34552869, 2021). "The expression level of FGF1 and FGFR1 in these cancers indicated that FGF1 induce the invasion and metastasis of tumor cells." (PMID 34552869, 2021). "In vivo, down-regulation of FGF1 expression delayed the occurrence and progression of tumors and effectively improved the nutritional status of tumor-bearing mice." (PMID 34552869, 2021). "We next performed a cluster analysis to consider the combined effects of tumor volume and FGF1 expression level." (PMID 34552869, 2021). "In cancer cells, amplified FGF1 expression promotes the proliferation and migration ability of tumor cells." (PMID 34552869, 2021). "The role of FGF1 in CRC tumor growth was analyzed by establishing an in vivo xenograft model using wild-type and FGF1-KD HCT116 cells." (PMID 34552869, 2021).
tumor (continued). "Applications of scFv against fibroblast growth factor receptor (FGFR) and fibroblast growth factor 1 (FGF-1) have shown a great anti-tumor effect both in vitro and in vivo." (PMID 33488587, 2020). "In conclusion, AKR1B10 acts as a tumor suppressor in CRC by inactivating FGF1, and is a novel target for combination therapy of CRC." (PMID 32615540, 2020). "The likely mechanism underlying the inhibitory effect of AKR1B10 is the induction of an anti-tumor inflammatory response by targeting FGF1, which is related to the growth and migration of CRC cells." (PMID 32615540, 2020). "Cell culture supernatants of the Mock and FGFR2-Fc–expressing tumor cells were collected to assess the specific binding of FGFR2-Fc to FGF1 and FGF2." (PMID 32076044, 2020). "The expression of FGF1 has a strong relationship with a poor prognosis and chemoresistance of tumours." (PMID 32660514, 2020). "Genome-wide expression profiling identified a group of genes within the angiogenesis pathway, including angiopoietin-like 4 (Angptl4), fibroblast growth factor 1 (Fgf1), and pleiotrophin (Ptn) as targets of activated PPARγ favoring tumor angiogenesis." (PMID 32785018, 2020). "EV-miR-15a, miR-181b, miR-320c and miR-874 from liver stem-like cells inhibit the migration and tube formation of tumor-derived endothelial cells and potential tumor angiogenesis by downregulating FGF1 and PLAU." (PMID 32503543, 2020). "A coculture system was utilized to analyze the effects of PAM on the secretion of FGF-1 by CAFs, with the aim of understanding the change in the tumor environment when PAM is applied as a therapeutic agent." (PMID 33097755, 2020). "Tumor derived endothelial cells (TDECs) were stimulated with fibroblast growth factor 1 (FGF1) or VEGF and formed more tubes compared with untreated, whereas cells treated with Sulforaphane had less tube formation." (PMID 30975732, 2019). "Together, these results revealed that CUX1/FGF1/HGF signalling is the main target of DPPA in the inhibition of tumour angiogenesis." (PMID 30010249, 2018). "We show that mast cells secrete increased amounts of granzyme b upon therapy, which mobilizes pro-angiogenic laminin- and vitronectin-bound FGF-1 and GM-CSF from the tumor matrix." (PMID 28814715, 2017). "Using cancer cells that stably express WT FGF1 or R50E, we showed that WT FGF1 markedly enhanced tumour growth and R50E suppressed it." (PMID 28302677, 2017). "Here, the authors show that mast cells mediate resistance to anti-angiogenetic inhibitors by altering the proliferative and organizational state of endothelial cells through mobilization of FGF-1 and GM-CSF from the tumor matrix and secretion of FGF-2." (PMID 28814715, 2017). "Various studies have shown correlations between fgf1 expression levels and both prognosis severity and tumor chemoresistance." (PMID 29048426, 2017). "MCF-7 cells that stably express FGF-1 facilitate the growth and metastasis of tumours when transplanted into nude mice 29,30, indicating that FGF-1 plays important roles in the pathological processes of cancer." (PMID 25124967, 2014). "Here we describe that R50E suppressed tumor growth in vivo while WT FGF1 enhanced it using cancer cells that stably express WT FGF1 or R50E." (PMID 23469107, 2013). "In the present study, we establish that R50E suppressed tumor growth in vivo while WT FGF1 enhanced it using cancer cells that stably express WT FGF1 or R50E." (PMID 23469107, 2013). "Growth rates of VEGF121 and VEGF165 transfectants were significantly higher than vector controls and essentially equal to each other, while FGF-1 tumours grew at a somewhat less rapid rate." (PMID 14735189, 2004). "We thank Dr Lurong Zhang of the Lombardi Cancer Center, Georgetown University Medical Center, for providing the FGF-1-transfected MCF-7 tumour cell line." (PMID 14735189, 2004).
tumor (continued). "In the current studies, FGF-1 overexpression led to a substantial increase in tumour growth rate, with a significant decrease in the perfused vessel spacing." (PMID 14735189, 2004). "In contrast, expression of VEGF121, VEGF165, or FGF-1 not only increased the frequency of MCF-7 tumour formation but also dramatically enhanced tumour growth." (PMID 14735189, 2004). "Given our findings that RORγ promotes cell survival and upregulates FGF1 expression in tumor cells, we investigated whether FGF1 mediates RORγ-dependent survival in iCCA cells." (PMID 41430037, 2025). "Moreover, CAFs promote tumor growth, spread, and invasion by releasing significant levels of mitogenic factors, including fibroblast growth factor-1 (FGF-1) and hepatocyte growth factor (HGF)." (PMID 40369674, 2025). "In tumor angiogenesis, FGF-1 and FGF-2 promote endothelial cell proliferation." (PMID 38111673, 2024). "This suggests that FGF1 could potentially affect tumor progression through its influence on metabolic disorders." (PMID 39737179, 2024). "WNT7A and FGF1 overexpression can induce tumor growth, leading to poor disease outcomes." (PMID 39766329, 2024). "Solely, FGF1 expression was inversely correlated with tumor size (r = – 0.05, p = 0.03)." (PMID 39302921, 2024). "In breast adipose tissue, FGF1 production may stimulate cancer cell proliferation and tumor progression." (PMID 37608351, 2023). "FGF1 can be released from apoptotic or necrotic cancer cells into the tumor microenvironment where it can influence other cancer cells and can also be produced by surrounding adipocytes or stromal cells and contained in the extracellular matrix, as we have described." (PMID 37608351, 2023). "In order to test whether the RES and/or FGF1 treatment could affect the efficacy of DOX for inhibiting tumor cell proliferation, we utilized the CCK-8 assay to ascertain the viability of HepG2 cells." (PMID 36110535, 2022). "In the intraperitoneal metastatic microenvironment, CAFs govern the metastatic cascade, including the adhesion, proliferation, invasion, and colonization of metastatic sites via increasing production of several molecules (CXCL12, IL-6, VEGFA, TGF-α, and β, FGF-1) within the tumor microenvironment." (PMID 35216340, 2022). "In tumors, FGF1 may be derived from both tumor and surrounding stromal cells and may have both paracrine or autocrine activity." (PMID 36064310, 2022). "We and others have previously shown that metabolic dysfunction, weight gain, and adipocyte hypertrophy are associated with increased production of FGF-1 in subcutaneous adipose tissue, and activation of FGFR signaling is associated with tumor growth and resistance to endocrine therapy." (PMID 35725493, 2022). "The differentiation of tumor-infiltrating MSCs to CAFs can be facilitated by FGF1." (PMID 36064310, 2022). "In conclusion, FGF1 acts as a tumor activator in CRC, and against FGF1 may provide a new visual field on treating CRC, especially for mTORC1-targeted resistant patients." (PMID 34552869, 2021). "As reported, studies suggested that FGF1 may promote proliferation and metastasis of tumor cells by regulating the AKT-mTOR-S6K1 signaling pathway in a variety of tumors." (PMID 34552869, 2021). "Furthermore, FGF1 mRNA levels in situ were markedly affected the weight of Subcutaneous tumor, and showed significant statistical correlation." (PMID 34552869, 2021). "High angiogenic activity in early tumor tissues may be an important factor in promoting the gradual increase of FGF1 expression." (PMID 34552869, 2021). "The efficacy of the developed GAG microarrays was first validated by FGF1, which is a member of a large family of growth factors that are involved in cell proliferation, development, and tumor angiogenesis and serves as a representative protein with binding specificity to sulfated GAGs." (PMID 34375459, 2021). "Knockdown of AKR1B10 promoted tumor growth in vivo, and increased the expression of FGF1." (PMID 32615540, 2020).
tumor (continued). "We selected fructose‐1,6‐bisphosphatase 1, FBP1, encoding the gluconeogenesis regulatory enzyme, acting as a rate‐limiting enzyme in gluconeogenesis and a well‐known tumor suppressor in HCC, and fibroblast growth factor 1, FGF1, encoding a well‐known pro‐oncogenic growth factor in HCC." (PMID 29117471, 2018). "FGF1 stimulation could remarkably increase tumour invasion with normal FGFR2 expression, but the invasion of RBE or HuCCT‐1 was decreased when FGFR2 was knocked down and increased when SPRY2 was knocked down." (PMID 30160357, 2018). "Another interesting issue need to be further investigated is whether the FGF1 secreted by the tumor cell may act in a paracrine manner to affect the surrounding stromal cells, which in turn facilitates the development and progression of PTC." (PMID 29632659, 2018). "Correlation between fgf1 expression, prognosis severity and tumor chemoresistance has been found." (PMID 29048426, 2017). "By analyzing tumor-conditioned media for free pro-angiogenic factors we could detect increased amounts of FGF-1 or GM-CSF in response to DC101 treatment only in the presence of WT- but not GZMB-deficient MC." (PMID 28814715, 2017). "Taken together, our results suggest that R50E suppresses angiogenesis induced by FGF1 and thereby may indirectly suppress tumorigenesis, in addition to its possible direct effect on tumor cell proliferation in vivo." (PMID 23469107, 2013). "Finally, FGF-1 transfectants have also been reported to form large, vascularised tumours and to confer a more malignant phenotype upon MCF-7 cells, without oestrogen supplementation." (PMID 14735189, 2004). "However, as FGF1 administration is generally known to promote cancer cell proliferation, survival and tumor angiogenesis, the types of cancer cells inhibited from proliferation, invasion and migration by FGF1-PIGN administration may be limited." (PMID 38637316, 2024). "Furthermore, FGF/FGFR trapping by AZD4547 could block the LHX2/FGF1-induced promotion of tumour growth and metastasis." (PMID 35864158, 2022). "However, it is important to notice that FGF1 interacts with all FGFRs and this broad specificity may be disadvantageous in the clinic in targeting a particular tumor type." (PMID 34635096, 2021). "To further clarify the regulatory relationship between FGF1 and mTOR related signaling pathways, we knocked down the expression of FGF1, analyzed the expression alteration of mTOR and its downstream targets, and evaluated the proliferation and migration ability of tumor cells in vitro and in vivo." (PMID 34552869, 2021). "We performed DNA methylation analysis of the encoding genes FGFR1, FGFR2, FGFR3, FGFR4, FGF1-14, FGF16-23, and CCND1 at single CpG site resolution (840 CpG sites) employing The Cancer Genome Research Atlas (TCGA) HNSCC cohort comprising N = 530 tumor tissue and N = 50 normal adjacent tissue samples." (PMID 34933671, 2021). "FGF1 expression was noted in our study in similar manner as PDGF BB—oral scars lack FGF1 in mesenchymal cells, while 50% of the skin scars had FGF1 mesenchymal cells positivity, statistically associated with the limbs location and residual tumor present in the vicinity of the scar." (PMID 30622976, 2018). "However, whether FGF1 was involved in the tumor-suppressive effects of HOTAIR knockdown needed to be further studied." (PMID 26183397, 2015). "The possible mechanism is that angiogenesis in the tumor may be driven by additional factors, such as fibroblast growth factor 1 (FGF-1), FGF-2, transforming growth factor-β (TGF-β), platelet-derived endothelial cell growth factor (PD-ECGF), and placental growth factor (PIGF)." (PMID 23799045, 2013). "This protein plays a role in many different functions, particularly with the fibroblast growth factor 1 (FGF1) gene function in cell growth and tumor invasion." (PMID 41471728, 2025).